RETN (resistin)
Diseases named in the same sentence as RETN in open-access papers (continued):
Sharing a sentence is not in itself a finding about the gene and the disease.
adenoma (3 papers, 2010 to 2025). A neoplasm arising from the epithelium. "Adipocytes secrete molecules such as adiponectin, CTRP1, leptin, osteopontin, and resistin, which may stimulate aldosterone production in addition to the aldosterone-secreting adenoma." (PMID 37452142, 2023). "Several interactions only occurred in specific locations, such as signalling pathways of CALCR, RANKL and TWEAK in the submucosa, GDNF, GDF, IL12, CD30 and CD137 signalling pathways in the adenoma, and PD‐L1, GP1BA, RESISTIN and SPP1 signalling pathways in tumour." (PMID 39934971, 2025).
Anxiety (3 papers, 2017 to 2025). Intense feelings of nervousness, tension, or panic often arise in response to interpersonal stresses. "However, some studies in non-pregnant women have reported that adiponectin, adipsin, leptin, and resistin may be associated with depressive and anxiety symptoms." (PMID 40565847, 2025). "As shown, significant higher correlations were observed between leptin, resistin, and anxiety symptoms (HARS scores) in the symptomatic groups (p < 0.004)." (PMID 40565847, 2025). "Adiponectin, leptin, and resistin levels positively correlated with anxiety symptoms (HARS, p < 0.01)." (PMID 40565847, 2025). "Pro-inflammatory properties of leptin and resistin may contribute to the severity of anxiety symptoms." (PMID 40565847, 2025). "Similarly, after controlling our variables for BMI, leptin and resistin displayed significantly high correlations with high levels of anxiety (HARS, p < 0.005), while adiponectin showed also an association with anxiety symptoms (HARS, p = 0.01)." (PMID 40565847, 2025). "To evaluate whether HFD and ApN or resistin treatment impact behavioral performance, we subjected mice to an open field test to assess for anxiety and general behavioral activity." (PMID 37732123, 2023). "However, the possible role of leptin and resistin as a pathophysiologic mechanism in the generation of anxiety-like behavior is not completely understood." (PMID 28463967, 2017).
cardiac arrest (3 papers, 2019 to 2023). Cessation of breathing and/or cardiac function. "The aim of our study was to evaluate the potential role of resistin in estimating the 30 days prognosis in patients with hypoxic-ischemic organ injury who survived after a cardiac arrest (CA)." (PMID 30650128, 2019). "In this study, we selected four proinflammatory cytokines (adiponectin, resistin, FABP4, and visfatin), which have not been investigated in cardiac arrest yet, to explore their possible predict values in predicting outcome of patients post ROSC." (PMID 32015774, 2020).
cerebrovascular diseases (3 papers, 2012 to 2021). "Similarly, subjects with allele 299A (allele +299 (G>A) alleles) exhibited high glucose levels at birth, and in diabetic patients, the resistin levels correlated with cerebrovascular disease especially in males." (PMID 30405857, 2018).
Crohn disease (3 papers, 2017 to 2024). A gastrointestinal disorder characterized by chronic inflammation involving all layers of the intestinal wall, noncaseating granulomas affecting the intestinal wall and regional lymph nodes, and transmural fibrosis. "Another adipokine hyperexpressed in mesenteric fat in Crohn's disease is resistin." (PMID 28127306, 2017). "Mesenteric fat seems to be involved in the pathogenesis of Crohn's disease: adipocytes in mesenteric fat can produce inflammatory cytokines such as TNF-alpha, IFN-gamma, IL-6, and IL-1 and other adipokines as leptin and resistin." (PMID 28127306, 2017). "Among these leptin, resistin, adiponectin, and SRFP5 appear to present a promising key role in the development and suppression of the inflammatory response, and their role has been confirmed in other inflammatory disorders, such as Crohn’s disease." (PMID 38338780, 2024).
Cushing syndrome (3 papers, 2013 to 2016). Cushing's syndrome (CS) encompasses a group of hormonal disorders caused by prolonged and high exposure levels to glucocorticoids that can be of either endogenous (adrenal cortex production) or exogenous (iatrogenic) origin. "In addition, human resistin levels were positively linked with salivary cortisol in depressed patients which is in line with a study reporting higher plasma resistin levels in women suffering from Cushing's syndrome." (PMID 24109426, 2013). "Elevated resistin levels were found in patients with Cushing’s syndrome; however, a curative surgery did not influence resistin concentration despite a fall in UFC and improved insulin sensitivity." (PMID 25129652, 2015).
diabetic foot (3 papers, 2010 to 2023). A diabetic foot is a foot that exhibits any pathology that results directly from diabetes mellitus or any long-term (or "chronic") complication of diabetes mellitus. "Our group reported that compared to diabetics without diabetic foot, diabetic subjects with diabetic foot had higher IL-6 and resistin plasma levels, and lower adiponectin plasma levels, as possible determinants of higher cardiovascular risk." (PMID 28056981, 2017).
esophageal cancer (3 papers, 2014 to 2025). A primary or metastatic malignant neoplasm involving the esophagus. "Elevated resistin levels have been reported in cachectic patients with gastric and esophageal cancer cachexia, and resistin levels are inversely correlated with BMI." (PMID 40869331, 2025). "It has been shown that increased level of resistin was related to TMN stage and primary tumor progression of gastric and esophageal cancer." (PMID 25049439, 2014).
esophageal squamous cell carcinoma (3 papers, 2020 to 2023). Esophageal squamous cell carcinoma (ESCC) is a type of esophageal carcinoma (EC) that can affect any part of the esophagus, but is usually located in the upper or middle third. "Thus, it was suggested that resistin could be a potential biomarker for squamous cell carcinoma of the esophagus." (PMID 36834693, 2023). "Interestingly, higher adiponectin levels were found in patients with esophageal squamous cell carcinoma (SCC) than in patients with esophageal adenocarcinoma, and resistin may be a biomarker for esophageal SCC." (PMID 33167521, 2020).
injury (3 papers, 2010 to 2021). Damage inflicted on the body as the direct or indirect result of an external force, with or without disruption of structural continuity. "• Plasma resistin levels were highly associated with GCS scores after traumatic brain injury." (PMID 21029428, 2010). "Increased resistin concentrations were reported after head trauma or intracerebral bleeding." (PMID 24070260, 2013).
Kawasaki disease (3 papers, 2012 to 2025). A rare inflammatory disease characterized by an acute febrile, systemic, self-limiting, medium-vessel vasculitis primarily affecting children. "This study investigated the association of the RETN promoter polymorphism with Kawasaki disease (KD) and its clinical parameters in Chinese children." (PMID 22577247, 2012). "Elevated RETN expression serves as an inverse biomarker for coronary artery lesions (CALs) in Kawasaki disease (KD) patients." (PMID 40636515, 2025).
lipodystrophy (3 papers, 2011 to 2017). A congenital or acquired disorder characterized by abnormal loss or redistribution of the adipose tissue in the body. "More recent studies have associated nucleotide variations in resistin and β2 adrenegic receptor (ARβ2) with the occurrence of lipodystrophy." (PMID 21939545, 2011). "Mice with adipose-specific deletion of PPARγ exhibit lipodystrophy and dramatically decreased serum adiponectin and resistin levels when compared with wild type mice." (PMID 28515350, 2017). "Our aim was to evaluate adipocyte-derived hormones (adiponectin, leptin, resistin, TNF-α, PAI-1) and ghrelin plasma levels and their relationship with IR in HIV-infected patients according to the presence of lipodystrophy and fat redistribution." (PMID 24958357, 2014).
oral cancer (3 papers, 2018 to 2020). "We suggest that tobacco smoking and betel-nut chewing in combination with RETN polymorphisms can increase the risk of rapid progression to oral cancer; thus, patients with a higher RETN polymorphism need to be aware of their higher risk of oral cancer." (PMID 30406149, 2018).
osteosarcoma (3 papers, 2019 to 2020). A usually aggressive malignant bone-forming mesenchymal neoplasm, predominantly affecting adolescents and young adults. "We then investigated the signaling pathways underlying resistin-induced VEGF-A-dependent angiogenesis in human osteosarcoma cells." (PMID 31719210, 2019). "Other reports have shown that resistin promotes angiogenesis in osteosarcoma and proliferation of smooth muscle cells through p44/p42 MAPK (ERK1/2) signaling." (PMID 32420377, 2020). "In conclusion, resistin is expressed at high levels in osteosarcoma and correlates with clinical stages of this disease." (PMID 31719210, 2019). "We therefore compared resistin IHC scores with the VEGF-A profiles we had previously obtained from clinical osteosarcoma tissue samples and found a highly positive relationship between resistin and VEGF-A expression." (PMID 31719210, 2019). "When we examined resistin expression profiles in human osteosarcoma tissue specimens, we found that higher resistin expression significantly correlated with increasing tumor stage." (PMID 31719210, 2019). "Our analyses revealed that resistin time-dependently stimulates VEGF-A production in human osteosarcoma cells via the ERK, JNK and p38 pathway, which subsequently increased EPC migration, tube formation and tumor angiogenesis." (PMID 31719210, 2019). "As our IHC results indicated that levels of resistin expression correlate with VEGF-A expression in human osteosarcoma specimens, we then sought to determine whether resistin promotes VEGF-A expression in human osteosarcoma." (PMID 31719210, 2019). "Similarly, in our study, IHC results from clinical osteosarcoma specimens showed that resistin and VEGF-A expression levels were positively correlated with increasing tumor stage." (PMID 31719210, 2019). "Thus, resistin may represent a new molecular therapeutic target in osteosarcoma angiogenesis and metastasis." (PMID 31719210, 2019). "However, there are few studies of resistin in relation to osteosarcoma." (PMID 31719210, 2019). "Our results showed that resistin increased levels of VEGF-A expression and secretion in osteosarcoma cells." (PMID 31719210, 2019). "However, whether resistin has a role in osteosarcoma angiogenesis is unclear." (PMID 31719210, 2019). "In this study, CM from resistin-treated osteosarcoma cells enhanced EPC migration and tube formation (VEGF-A served as the positive control), indicating that EPCs may be recruited to the tumor microenvironment and form new blood vessels via resistin-promoted VEGF-A expression." (PMID 31719210, 2019).
rectal cancer (3 papers, 2012 to 2025). A primary or metastatic malignant neoplasm that affects the rectum. "In subgroup analyses, we found that higher resistin concentrations were associated with a higher risk of rectal cancer in men and in individuals with more than 6 h of fasting before the blood collection in the current study." (PMID 36428592, 2022). "In this analysis, the relative risk of rectal cancer per doubling resistin concentrations among men was 1.13; 95% CI: 0.70–1.82." (PMID 36428592, 2022). "However, among men, doubling resistin concentrations were related to 1.53-fold the risk of rectal cancer (95% CI: 1.01–2.33)." (PMID 36428592, 2022). "In patients suffering from rectal carcinoma, resistin correlates positively with tumor size based on T-staging (r=0.49; p<0.01) and tumor grading (r=0.39; p=0.02)." (PMID 23173608, 2012).
renal fibrosis (3 papers, 2021 to 2025). A final common manifestation of a wide variety of chronic kidney diseases characterized by glomerulosclerosis and tubulointerstitial fibrosis. "Visceral adipose tissue secretes pro-inflammatory cytokines and adipokines, such as leptin and resistin, which not only induce oxidative stress but also promote renal fibrosis and dysfunction." (PMID 39940350, 2025). "Several synthesized adipokines, including but not limited to leptin, adiponectin, vascular endothelial growth factor, angiopoietins, and resistin, play crucial roles in extracellular matrix accumulation, ultimately culminating in renal fibrosis." (PMID 38139229, 2023). "Many adipokines, including leptin, adiponectin, vascular endothelial growth factor, angiopoietins, and resistin, play crucial roles in the accumulation of extracellular matrix, ultimately leading to renal fibrosis." (PMID 38139229, 2023). "Many adipokines, including leptin, adiponectin, vascular endothelial growth factor, angiopoietins, and resistin, play a role in extracellular matrix accumulation, leading to renal fibrosis." (PMID 34940593, 2021).
rheumatic diseases (3 papers, 2011 to 2012). "This study also revealed a strong positive correlation between resistin and IL-1 receptor antagonist, the serum level of which is elevated in many rheumatic diseases, whereas bone mineral density was inversely correlated with serum resistin." (PMID 22584415, 2012). "In addition, resistin has a role as a marker of inflammation in other rheumatic diseases, such as systemic lupus erythematous (SLE)." (PMID 22910888, 2012).
septic shock (3 papers, 2016 to 2024). Shock caused by infection; frequently caused by gram negative bacteria, although some cases have been caused by other bacteria, viruses, fungi, and protozoa; characterized by fever, chills, tachycardia, tachypnea, and hypotension. "Thirteen patients with septic shock and six control patients were analyzed for serum resistin levels and their effects on neutrophil migration." (PMID 28779451, 2017). "Patients with septic shock had higher serum resistin levels than control ICU patients and showed a strong, negative correlation between hyperresistinemia and neutrophil transwell migration (ρ= − 0.915, p < 0.001)." (PMID 28779451, 2017). "From a potentially therapeutic perspective, we would be interested in whether hemoadsorption of resistin can rescue primary neutrophil function in septic shock patients." (PMID 28779451, 2017). "However, there is a very strong, direct correlation between plasma resistin concentrations and inhibition of NB4PMN transwell migration in patients with septic shock and hyperresistinemia, i.e., plasma resistin concentrations >20 ng/mL." (PMID 28779451, 2017). "Similarly to the septic shock cohort, high levels of both HBP and resistin were detected in plasma of STSS patients, and demonstrated an even stronger correlation (r = 0.8, p = 0.016)." (PMID 26887258, 2016). "All septic shock patients had elevated levels of plasma HBP and resistin as compared to critically ill non-infectious patients, and a positive correlation between plasma HBP and resistin levels was found in all patient cohorts (i.e. Gram-positive and Gram-infections, STSS caused by GAS." (PMID 26887258, 2016).
adrenal incidentalomas (2 papers, 2015 to 2022). "Increased serum resistin was also reported in subjects with adrenal incidentalomas displaying subclinical hypercortisolaemia." (PMID 25129652, 2015).
Arrhythmia (2 papers, 2016 to 2023). Any cardiac rhythm other than the normal sinus rhythm. "We next examined the functional implications of sitagliptin-attenuated resistin secretion, and found that resistin played an important role in sympathetic innervation and arrhythmias through modulation of NGF levels." (PMID 26811539, 2016). "This study determined plasma resistin levels before surgery to assess the baseline concentrations and the environment in which arrhythmia may develop." (PMID 36624488, 2023). "The aim of the present study was to investigate whether sitagliptin regulates resistin expression, and to investigate the molecular mechanism involved and the possible functional relevance of this regulation on arrhythmia in a rat MI model." (PMID 26811539, 2016). "Our results suggest that the mechanisms of sitagliptin-induced anti-arrhythmias were related to an attenuated NGF expression through a resistin-dependent pathway, and that the resistin expression was coupled to the regulation of GIP." (PMID 26811539, 2016).
Atopic Dermatitis (2 papers, 2013 to 2018). "This study tested the association between G>A (rs3745367) and C>T (rs3219177) single nucleotide polymorphisms (SNPs) of the RETN gene with atopic dermatitis." (PMID 29584687, 2018). "Resistin is an adipokine expressed mainly in macrophages and monocytes; it has a role in the inflammatory process and is associated with multiple inflammatory human diseases; however, only few studies linked resistin to atopic dermatitis." (PMID 29584687, 2018). "However, to date, only a few studies linked resistin to atopic dermatitis." (PMID 29584687, 2018). "Another example is impairment of thyroid function, which was shown to decrease resistin, and to augment atopic dermatitis." (PMID 29584687, 2018). "For example, exercise has been shown to trigger or worsen atopic dermatitis due to sweating, and it was reported to decrease levels of resistin." (PMID 29584687, 2018). "For the serum resistin levels, a significant decrease was indicated in atopic dermatitis patients compared to healthy subjects (p < 0.05)." (PMID 29584687, 2018). "Thus, the exact mechanisms by which decreases in resistin levels contribute to the etiology of atopic dermatitis need further investigations." (PMID 29584687, 2018). "Alternatively, factors that might contribute to the development of atopic dermatitis might negatively influence resistin levels." (PMID 29584687, 2018). "In addition, it explored the relationship between serum resistin protein and atopic dermatitis." (PMID 29584687, 2018).
brain infarction (2 papers, 2013 to 2016). Tissue necrosis in any area of the brain, including the cerebral hemispheres, the cerebellum, and the brain stem. "Recent research on genome-wide associations has implicated that the serum resistin level and its gene polymorphism are associated with cerebral infarction (CI) morbidity and prognosis, and could thereby regulate CI." (PMID 27699082, 2016). "It seems unlikely that resistin leaked from the injured brain into the systemic circulation since some brain-dead individuals with severe brain infarction had only modest increases in resistin levels." (PMID 24070260, 2013).
brain ischemia (2 papers, 2016 to 2024). Diminished or absent blood supply to the brain caused by obstruction (thrombosis or embolism) of an artery resulting in neurologic damage. "Meanwhile, the cortical resistin mRNA level increased in the animal brain ischemia and brain injury models, which thereby reminds us that there is a relationship between CI incidence and serum resistin level together with its gene polymorphism." (PMID 27699082, 2016).